EMP1 (epithelial membrane protein 1)
Synonyms: EMP-1; TMP; CL-20
Tractability: Antibody: its Gene Ontology location is reachable by antibodies, with high confidence; UniProt predicts a signal peptide or a membrane-spanning region.
Gene: Protein-coding gene on chromosome 12 (13,196,723 to 13,219,941, forward strand). Ensembl gene ENSG00000134531.
Subcellular location: Membrane
Subcellular location (Human Protein Atlas): Vesicles
Gene Ontology:
Molecular function: protein binding
Biological process: apoptotic process; bleb assembly; epidermis development
Cellular component: plasma membrane; membrane
Genetic constraint (gnomAD): Loss-of-function variants: 5 observed, 16.71 expected, observed/expected ratio (o/e) 0.3, 90% interval 0.16 to 0.63. The upper end of that interval is the gene's LOEUF score, 0.63, which puts it in group 2 of 6, group 1 being the genes least tolerant of losing a copy. Missense variants: 166 observed, 204.14 expected, observed/expected ratio (o/e) 0.81, 90% interval 0.72 to 0.93. Synonymous variants: 78 observed, 81.13 expected, observed/expected ratio (o/e) 0.96, 90% interval 0.8 to 1.16.
Homologues: Orthologues: chimpanzee EMP1 (97% identical), dog EMP1 (84% identical), pig EMP1 (79% identical), mouse Emp1 (77% identical), guinea pig EMP1 (75% identical), rat Emp1 (74% identical), rabbit EMP1 (67% identical), macaque EMP1 (61% identical), tropical clawed frog emp1 (59% identical), zebrafish emp1 (37% identical). Paralogues in human: PMP22 (40% identical), EMP2 (39% identical), EMP3 (33% identical), LIM2 (23% identical), TMEM202 (22% identical), GSG1L (20% identical), GSG1L2 (19% identical), CLDND2 (18% identical), NKG7 (16% identical), GSG1 (15% identical).
Diseases named in the same sentence as EMP1 in open-access papers:
EMP1 is named in the same sentence as 92 diseases in open-access papers, as found by Europe PMC text mining. Sharing a sentence is not in itself a finding about the gene and the disease. The quoted sentences say what the papers report.
gastric cancer (15 papers, 2019 to 2025). A primary or metastatic malignant neoplasm involving the stomach. "Alterations of EMP1 expression have been linked to a variety of human cancers like gliomas, gastric cancer as well as in oral, laryngeal, scirrhous gastric, and esophageal cancers." (PMID 31450568, 2019). "EMP1 is mainly expressed in the early and immature neurons and glioma, and in sclerotic gastric carcinoma cells." (PMID 37547756, 2023). "Next, we discovered that transfection of si-EMP1 into the SGC7901/DDP cell line with miR-95-3p exerted a profound effect on the progression of gastric cancer." (PMID 33714198, 2021). "Consistent with the tumor suppressive activity of EMP1 in esophageal cancer, EMP1 protein expression is lower in gastric cancer than in normal tissues." (PMID 31652725, 2019). "According to previous reports, EMP1 regulates cell proliferation and differentiation, and its expression of EMP1 is specifically high in many cancers, such as gastric cancer, glioma, and colorectal cancer, indicating that EMP1 is a novel therapeutic target for cancer therapy." (PMID 41285728, 2025). "Similarly, MicroRNA-95-3p-mediated targeting of EMP1/PI3K/AKT signaling confers cisplatin resistance in gastric cancer." (PMID 41458590, 2025). "EMP1 is highly expressed in gastric cancer, glioma, early neurons, and immature neurons." (PMID 36217151, 2022). "Overall, this suggests that EMP1 can reverse DDP-resistance in gastric cancer." (PMID 33714198, 2021). "EMP1 is an integral transmembrane glycoprotein, which has been identified as a poor prognostic factor in human cancers such as pediatric acute lymphoblastic leukemia, gliomas, gastric cancer, etc." (PMID 31892991, 2020). "A previous study suggested that epithelial membrane protein 1 (EMP1) gene could prevent tumor proliferation and was associated with gastric carcinoma." (PMID 31622349, 2019). "However, EMP1 has been reported as an oncogene in gastric cancer." (PMID 41284206, 2025). "Additionally, EMP1 is downregulated in gastric cancer tissues compared to normal tissues." (PMID 33714198, 2021). "A study on the development of drug resistance in gastric cancer using microRNAs (miRNAs) and cisplatin (DDP) showed that EMP1 was the target of miR-95-3p." (PMID 36217151, 2022). "Overall, we conclude that miR-95-3p help develop resistance to DDP and promote cell proliferation, migration, and invasion by down-regulating EMP1 and increasing the phosphorylation of PI3K/AKT pathway in gastric cancer." (PMID 33714198, 2021).
breast carcinoma (14 papers, 2017 to 2025). "EMP1 has also is a bio-marker for HER-2 activation in breast cancer and is associated with lymph node metastasis in squamous cell carcinoma of the oral cavity." (PMID 37547756, 2023). "The mRNA expression of EMP1 is upregulated in glioma and breast cancer, and associated with the expression of myc and ERBB2 receptors." (PMID 36217151, 2022). "has established EMP1’s critical involvement in breast cancer pathogenesis, its precise mechanistic role in TNBC remains to be elucidated." (PMID 41458590, 2025). "In this study, we examined the infiltration landscape of cell types in the TME of breast cancer, and found that EMP1 expression was positively correlated with stromal and microenvironmental scores." (PMID 40016223, 2025). "Gnirke demonstrated a correlation between the expression of EMP1 and its aggressive and metastatic properties in several human breast cancer cell lines with different metastatic characteristics." (PMID 41458590, 2025). "The GEPIA database analysis revealed significantly reduced EMP1 expression in breast cancer tissues compared to normal tissues." (PMID 41458590, 2025). "Among different subgroups in breast cancer scRNAseq data, significant correlations between EMP1/COL3A1 and three EMT genes (CDH1, VIM, and CTNNB1) were found in c16 fibroblasts." (PMID 38187400, 2023). "In breast cancer, for example, EMP1 functions as a new marker for lobular and ductal invasive breast carcinoma differentiation, as well as a putative link with breast cancer invasion promotion." (PMID 37008256, 2023). "The EMP1 protein level in breast cancer tissue samples significantly decreased and were significantly correlated with T stage, lymph node metastasis, and histopathologic grade." (PMID 36217151, 2022). "Enhancing EMP1 levels in breast cancer cells can induce apoptosis and inhibit invasion and migration." (PMID 36217151, 2022). "The EMP1 protein levels in nasopharyngeal carcinoma, prostate cancer, breast cancer, and colorectal cancer are significantly lower compared to normal tissues (p < 0.05)." (PMID 36217151, 2022). "EMP1 serves as a reliable marker that distinguishes the two most common histological types of breast cancer: invasive ductal and lobular carcinomas." (PMID 31652725, 2019). "Overexpression of EMP1 in breast cancer cells inhibits proliferation through reducing the expression of vascular endothelial growth factor (VEGF)-C, and attenuates cell migration and invasion." (PMID 31652725, 2019). "Similar to breast cancer, the opposing roles of EMP1 in cancer invasion and metastasis operate in prostate cancer." (PMID 31652725, 2019). "Initially, univariate Cox regression analysis revealed that 12 genes were associated with the prognosis of breast cancer, followed by LASSO analysis to derive a prognostic signature composed of 8 genes, including CERCAM, EMP1, SDC1, PRKG1, XG, TNN, WLS, and PDLIM4." (PMID 38728370, 2024). "However, reduced protein levels of the epithelial membrane protein 1 have been correlated with poor prognosis, and its overexpression in breast cancer cells inhibits their proliferative, and invasive behavior." (PMID 38937754, 2024). "Furthermore, we found enhanced expression of EMP1 in BoM-derived fibroblasts in breast cancer, and these cells were enriched in multiple cancer-related pathways, confirming the importance of these cells during the BoM process." (PMID 38187400, 2023). "In addition to LNCaP cells, we used human breast cancer MCF7 cells to more broadly certify the pathological role of EMP1 in cancer." (PMID 29867202, 2018). "We discovered a critical role for EMP1 in TME remodeling of BC, especially in triple-negative breast cancer (TNBC)." (PMID 40016223, 2025).
breast carcinoma (continued). "Through an integrated analysis of transcriptomics data, we identified a special subgroup of EMP1+/COL3A1+ fibroblasts that are enriched in breast cancer BoM samples, which might facilitate the BoM process through interacting with tumor cells via COL3A1-ADGRG1 communication." (PMID 38187400, 2023). "Consistent with this, UALCAN data demonstrated low EMP1 levels across all major molecular subtypes (Luminal, HER2+, and TNBC) of breast cancer." (PMID 41458590, 2025). "Worthy, the signature demonstrated to predict poor outcomes in breast cancer patients exhibiting high transcriptional levels of ITGA11, THBS1, FN1, EMP1, ITGA2, FYN, SPP1, and EMP2." (PMID 38937754, 2024). "Seven of the 15 TME prognostic genes (NOS2, SCG2, RGS3, EMP1, PDLIM4, PCDH9, and GFI1) were involved in enhancing cell proliferation, destroying cell apoptosis, promoting cell invasion, or migration in breast cancer." (PMID 36936167, 2023). "As expected, seven of the TME prognostic genes (NOS2, SCG2, RGS3, EMP1, PDLIM4, PCDH9, and GFI1) showed dual functions in breast cancer progression." (PMID 36936167, 2023). "Overexpression of EMP1 in LNCaP prostate cancer cells enhances cell migration and invasion, similar to the findings for MCF7 breast cancer cells and Caco2 colon adenocarcinoma cells." (PMID 31652725, 2019). "The similar effects of EMP1 are also observed in other types of cancer cell lines, MCF7 breast cancer cells and Caco2 colon cancer cells." (PMID 31652725, 2019). "Fibroblasts expressing high levels of EMP1 and COL3A may be involved in the metastatic processes of breast cancer, kidney cancer, and prostate cancer." (PMID 40433364, 2025).
colorectal cancer (14 papers, 2022 to 2026). A primary or metastatic malignant neoplasm that affects the colon or rectum. "In colorectal cancer, EMP1 was expressed in a unique high-relapse tumor cell population, which is the main reason for metastatic recurrence of colorectal cancer after surgery." (PMID 41285728, 2025). "In colorectal cancer, low EMP1 expression significantly correlates with advanced T stage, lymph node metastasis, clinical stage, and poor five-year survival." (PMID 41465326, 2025). "In colorectal cancer, oral squamous cell carcinoma, and laryngeal carcinoma, EMP1 functions as a tumor suppressor by inhibiting proliferation and inducing apoptosis." (PMID 41458590, 2025). "One latest study showed that EMP1 marked a subpopulation of colorectal cancer cells with remarkably enhanced tumor relapse, and genetic elimination of this EMP1high cell population halted metastatic recurrence." (PMID 37386026, 2023). "A recent study reported that EMP1 could be used as a positive target for liver metastasis in colorectal cancer." (PMID 41284206, 2025). "Interestingly, we did not observe an overlap between AF and LGR5+ cells in colorectal cancer tumors, suggesting that AF cells represent a distinct CSC population in colorectal cancer like EMP1+ cells." (PMID 39225547, 2024). "Further studies are needed to determine the exact role of AF colorectal cancer CSCs in tumor relapse (and perhaps in metastasis) as well as whether AF colorectal cancer CSCs coexpress other relevant markers like EMP1." (PMID 39225547, 2024). "Moreover, EMP1 is linked to nodal metastases in oral SCC43 and metastatic recurrence in colorectal cancer." (PMID 36708070, 2023).
renal cell carcinoma (12 papers, 2021 to 2025). "TAZ induces ferroptosis in renal cell carcinoma by upregulating epithelial membrane protein 1 (EMP1) expression, which promotes NADPH oxidase 4 (NOX4)." (PMID 40619484, 2025). "For example, in renal cell carcinoma, TAZ regulates expression of EMP1 and thus induces the expression of a renal-enriched ROS-generating enzyme essential for ferroptosis." (PMID 38812041, 2024). "In a model of renal cell carcinoma, the molecular mechanism for ferroptosis resistance in highly confluent cells involved TAZ-induced regulation of epithelial membrane protein 1 (EMP-1) and NADPH oxidase 4 (NOX4)." (PMID 35065965, 2022). "TAZ promotes ferroptosis by regulating epithelial membrane protein 1 (EMP1) and NOX4 in renal cell carcinoma." (PMID 33868986, 2021). "In renal cell carcinoma, at low cell density, activated TAZ promotes the expression of epithelial membrane protein 1 (EMP1), followed by upregulation of NOX4 levels." (PMID 34977044, 2021). "In renal cell carcinoma, TAZ stimulates the expression of the epithelial membrane protein 1 (EMP1), which in turn activates p38 MAPK and finally induces the accumulation of NOX4." (PMID 34572111, 2021). "Furthermore, there was a significant correlation between COL3A1 and EMP1 in c9 fibroblasts, confirming the existence of COL3A1+/EMP1+ cells during the bone metastasis process in renal cell carcinoma." (PMID 38187400, 2023). "The Hippo signaling pathway regulator transcription regulator 1 (TAZ) regulates ferroptosis through epithelial membrane protein 1 (EMP1)-NOX4, which means that ferroptosis may be a therapeutic target for renal cell carcinoma and other TAZ-activated tumors." (PMID 35688814, 2022). "Interestingly, TAZ, but not YAP, appears to specifically sensitize renal cell carcinoma cell lines to ferroptosis via regulation of epithelial membrane protein 1 (EMP1), suggesting a context-dependent role of YAP/TAZ in ferroptosis." (PMID 34485285, 2021).
glioma (11 papers, 2015 to 2025). A benign or malignant brain and spinal cord tumor that arises from glial cells (astrocytes, oligodendrocytes, ependymal cells). "Cross-referencing this list with our in-house RNA-Seq dataset shows several HDACi resistance genes that are expressed at higher baseline levels in our IDHwt glioma cells, including EMP1, WWTR1, EGFR, and AGRN." (PMID 41066183, 2025). "In glioma, EMP1 regulates the cell proliferation, migration, and stemness through PI3K-AKT signaling and CD44." (PMID 37008256, 2023). "Previous reports have shown that EMP1 can regulate CD44 expression in glioma stem cells, resulting in promoting of cancer cell stemness." (PMID 36217151, 2022). "In primary glioma cells, EMP1 gene silencing can significantly inhibit tumor proliferation and invasion." (PMID 36217151, 2022). "Increased EMP1 expression is also associated with increased tumor grade (p < 0.001) and poor prognosis (p < 0.001) in the TCGA, Rembrandt, and CGGA human glioma databases." (PMID 36217151, 2022). "EMP1 has been found to be a tumor promoter gene in pediatric leukemia, non-small cell lung cancer, and glioma." (PMID 34905506, 2021). "Activating the PI3K/Akt/mTOR signaling pathway greatly triggers EMP1-promoted glioma progression." (PMID 36217151, 2022). "Additionally, EMP1 silencing inhibits the invasion and proliferation of glioma cells by inhibiting the PI3K-Akt signaling pathway." (PMID 36217151, 2022). "Thus, to elucidate the effects of RF exposure on growth, apoptosis, and malignancy of human glioma cells, we analyzed c-myc, Emp-1, bcl-2, and bax expression by real-time PCR and Id-1 protein levels by western blotting." (PMID 26253141, 2015).
ovarian carcinoma (11 papers, 2012 to 2025). A malignant neoplasm originating from the surface ovarian epithelium. "In ovarian cancer, EMP1 is frequently upregulated, especially in advanced and chemoresistant cases, and high EMP1 expression is associated with poor prognosis, advanced stage, metastasis, and cisplatin resistance." (PMID 41465326, 2025). "Likewise, EHD2, ITGA8 and EMP1 has also been identified as tumor suppressor genes that when altered is associated with highly malignant ovarian cancers and germ cell tumors." (PMID 22737227, 2012). "In ovarian cancer, overexpressed EMP1 promotes tumor cell proliferation, invasion, and EMT via the MAPK signaling pathway." (PMID 40612666, 2024). "In this study, EMP1 was identified as a key gene for cisplatin resistance in ovarian cancer by bioinformatics, and it was verified in vitro and in vivo." (PMID 36708070, 2023). "On the contrary, EMP1 has been shown to be involved in cancer progression, including ovarian cancer and pediatric leukemia, which suggests that the anti-tumor or tumor-promoting action of EMP is dependent on the type of cancer." (PMID 33714198, 2021). "EMP1 expression correlates with immune cell infiltration (macrophages, neutrophils, dendritic cells) and high expression of immune checkpoints in the tumor microenvironment, especially in bladder and ovarian cancers." (PMID 41465326, 2025). "In contrast, EMP1 is upregulated in GBM, melanoma, leukemia, NSCLC, bladder cancer, and some ovarian cancers, where it promotes tumor cell migration, invasion, and metastasis." (PMID 41465326, 2025). "Particularly, siRNA-mediated knockdown of seven genes, CASC10, ATP11B, EMP1, GAS1, SLC6A15, GALNT13, and PDLIM3, significantly reduced cell proliferation of ovarian cancer cells." (PMID 35887085, 2022). "A multivariate analysis revealed that, after controlling for TGFB2 expression, four genes (CLIC3, ANPEP/LAP1, RIN2, and EMP1) showed negative correlations between mRNA expression and OS across all expression levels in an ovarian cancer cohort." (PMID 41465326, 2025). "In ovarian cancer, EMP1 was discovered to play a critical role as a negative regulator in ovarian serous tumors, and decreased EMP1 expression in serous tumors associated with increased disease severity." (PMID 37008256, 2023).